CDK4 (cyclin dependent kinase 4)
Diseases named in the same sentence as CDK4 in open-access papers (continued):
Sharing a sentence is not in itself a finding about the gene and the disease.
hidradenocarcinoma (1 paper, 2025). A carcinoma with apocrine and less often eccrine differentiation, arising from the sweat glands. "This case report describes the effective therapy of a 75‐year‐old female patient with metastatic hidradenocarcinoma with a combination of CDK4/6 and aromatase inhibitors." (PMID 40277279, 2025).
hypogonadism (1 paper, 2025). A disorder characterized by decreased function of the gonads. "Novel targeted agents, including PARP and CDK4/6 inhibitors, pose further issues by compromising follicular integrity and granulosa cell functionality, whereas immunotherapies and checkpoint inhibitors may induce primary or secondary hypogonadism." (PMID 41395617, 2025).
hypopituitarism (1 paper, 2009). A condition of diminution or cessation of secretion of one or more hormones from the anterior pituitary gland. "Interestingly, the pituitary deficiency induced by Prop1 mutations is reminiscent of the hypopituitarism induced by inactivation of the cell cycle regulator Cdk4." (PMID 19283075, 2009). "Indeed, the relative abundance of GPS numbers is altered in Cdk4-deficient mice, a model of hypopituitarism induced by the lack of this cyclin-dependent kinase." (PMID 19283075, 2009).
hypothyroidism (1 paper, 2024). Abnormally low levels of thyroid hormone. "The relative expression of three cell cycle promoters (CDK1, CDK2, and CDK4), and one cell cycle inhibitor (CDKN1A) was compared in each tissue to determine the effect of hypothyroidism on the developing fetus." (PMID 38902754, 2024).
Immunodeficiency (1 paper, 2016). Failure of the immune system to protect the body adequately from infection, due to the absence or insufficiency of some component process or substance. "Mutation of CDK4 was found to be associated with a variety of cancers and mutation of LCK was found to be associated with immunodeficiency." (PMID 26895224, 2016).
Intellectual disability (1 paper, 2025). "The extreme microcephaly in CDK4 individuals as well as the mild intellectual disability are characteristic features of primary microcephaly." (PMID 40210435, 2025).
intestinal neuroendocrine tumors (1 paper, 2014). "We have identified two subtypes of intestinal neuroendocrine tumors, both associated with metastases, that express common signaling pathways involved in neuroendocrine secretion, nervous system and neuroendocrine development, as well as hypoxia and cyclin/CDK4 regulation." (PMID 25023465, 2014).
intestinal tumors (1 paper, 2013). "In our study, we first used a genetic approach to explore the role of Cdk4 in reducing intestinal tumors in Apc−/+ mice." (PMID 23530816, 2013). "To further define a potential role for Cdk4 blockade in preventing intestinal tumor formation, we generated double mutant mice, Apc−/+Cdk4−/−, and compared them to control Apc−/+Cdk4+/+ mice." (PMID 23530816, 2013). "We evaluated the effect of Cdk4 blockade on the prevention of intestinal tumor formation by crossing Cdk4−/− mice to Apc−/+ mice." (PMID 23530816, 2013).
laryngeal squamous cell carcinoma (1 paper, 2013). A squamous cell carcinoma that arises from the larynx. "CDK4 overexpression was observed in laryngeal squamous cell carcinoma, which was significantly correlated with tumor size and an advanced stage." (PMID 23426899, 2013).
latent infection (1 paper, 2021). "This is consistent with previously reported roles of the CDKN2A/CCND1/CDK4 axis in NPC cell growth and persistent EBV latent infection in NPE cells." (PMID 34234122, 2021).
Lewis lung carcinoma (1 paper, 2016). "We found that CDDP, when administered with FGS, significantly decreased the viability and increased the apoptosis and cell cycle arrest of Lewis lung carcinoma (LLC) cells, which were associated with the increase of p21 and decreases of cyclin D1 and CDK4." (PMID 27721894, 2016).
liver diseases (1 paper, 2024). "Regarding possible regimens, the triggering event of obese pregnancy–associated liver disorders is phosphorylation of C/EBPα at Ser193 by CDK4." (PMID 37967813, 2024).
Luminal A (1 paper, 2025). "In Luminal A tumors, cell cycle regulatory systems like active p16INK4a and balanced CDK4/6 activity keep the G1/S step in arrest, leading to a slower growth phenomenon." (PMID 40017494, 2025).
malignant phyllodes tumor (1 paper, 2023). A phyllodes tumor with sarcomatous stroma. "MDM2 and/or CDK4 protein overexpression and gene amplification are beneficial ancillary studies that can help establish the diagnosis of primary breast ALT/WDLPS and DDLPS, and effectively rule out the diagnoses of malignant phyllodes tumor and metaplastic breast carcinoma." (PMID 37888062, 2023).
malnutrition (1 paper, 2025). Inadequate nutrition resulting from poor diet, malabsorption, or abnormal nutrient distribution. "As CDK4/6is are predominantly bound to plasma proteins and the global prevalence of malnutrition among older adults is high, the free fraction of CDK4/6is may be elevated in this vulnerable population." (PMID 41496429, 2025).
microcephaly (1 paper, 2025). A congenital or acquired developmental disorder in which the circumference of the head is smaller than normal for the person's age and sex. "Here we present evidence for CDK4 as a regulator of human brain and organism growth, identifying homozygous loss-of-function CDK4 mutations in individuals from two independent families with postnatal growth restriction and severe microcephaly." (PMID 40210435, 2025). "With CDK6 primary microcephaly previously reported, discovering CDK4 mutations as a cause for microcephaly seems on the face of it unsurprising." (PMID 40210435, 2025). "Notably, heterozygous frameshift and nonsense variants in CCND2 (encoding Cyclin D2), the partner of CDK4/6 with major roles in neural progenitor proliferation, also result in microcephaly." (PMID 40210435, 2025). "Here we identified biallelic mutations in CDK4 as a cause of microcephaly and short stature." (PMID 40210435, 2025). "With LOF mutations in the CDK4/6 binding partner CCND2 causing microcephaly, and GOF CCND2 mutations leading to brain overgrowth, we conclude that CDK4 and G1 Cyclin–CDK activity represents a key axis controlling human brain growth." (PMID 40210435, 2025). "Altogether, we identified homozygous variants in two phenotypically similar families, with affected individuals displaying nonsyndromic microcephaly and short stature, which appeared likely to result in abrogation of CDK4 function." (PMID 40210435, 2025). "Therefore, mitotic defects were unlikely to be the cause of the growth defect caused by CDK4 microcephaly mutations." (PMID 40210435, 2025). "Also, the predominantly postnatal nature of CDK4 microcephaly suggests that other processes contributing to brain volume could be impacted, such as gliogenesis, which peaks in the third trimester and continues postnatally." (PMID 40210435, 2025). "Hence, resulting hypocellularity likely accounts for microcephaly and growth failure in CDK4 cases." (PMID 40210435, 2025). "Cortical size is much more subtly affected in microcephaly mouse models and has not been investigated in Cdk4 KO mice." (PMID 40210435, 2025). "CDK4 and most CCND2 microcephaly individuals display similar growth restriction, with reduced growth parameters at birth of −1 to −2 SD but more significant microcephaly postnatally, suggestive of a prenatal-onset origin with a delayed presentation." (PMID 40210435, 2025). "Therefore, extreme microcephaly observed in both CDK6 and CDK4 cases do not share a common mechanism." (PMID 40210435, 2025).
microphthalmia (1 paper, 2023). Congenital or developmental anomaly in which the eyeballs are abnormally small. "A similar search of DR17 using the term microphthalmia resulted in 22 genes significant for the small eyes phenotype: Aldh1a3, Aff4, Bmp4, Cdk4, Cox6b1, Cxcr4, Dync1li1, Eef1d, Fgd1, Gne, Grh12, Mab21l2, Maf, Med13l, Mllt10, Mthfd2, Pex6, Phgdh, Ssr1, Stim1, Tdo2, and Vps26c." (PMID 36737727, 2023).
Myocardial fibrosis (1 paper, 2023). "Excessive activation of CDK4 has been implicated in the development of myocardial fibrosis and cardiac dysfunction." (PMID 38137541, 2023). "Research has demonstrated that inhibiting CDK4 can attenuate the extent of myocardial fibrosis and improve cardiac function in animal models of DCM." (PMID 38137541, 2023).
myotonic dystrophy (1 paper, 2023). An inherited progressive disorder affecting the muscles. "The high activity of Cdk4 in myotonic dystrophy cells during all stages of differentiation leads to impaired cell cycle withdrawal and muscle differentiation." (PMID 37673339, 2023).
nephritis (1 paper, 2023). Inflammation of renal tissue. "The precise mechanisms and specific roles of CDK4/6 inhibitors in treating various renal diseases, including AKI, CKD, PKD and other related nephritis, are still largely unknown." (PMID 37686364, 2023).
neurosarcomas (1 paper, 2015). "Furthermore, in a small number of MPNSTs, or neurosarcomas, CDK4 gene amplification and subsequent increased CDK4 expression are significant predictors of poor patient survival." (PMID 26528855, 2015).
opisthorchiasis (1 paper, 2024). Infection with flukes of the genus Opisthorchis. "For example, p16, encoded by p16INK4A (CDKN2A), is an inhibitor of CDK4, and the expressions of cyclin D1 and CDK4 are up-regulated in opisthorchiasis-associated CCA." (PMID 39236081, 2024).
Overgrowth (1 paper, 2024). Excessive postnatal growth which may comprise increased weight, increased length, and/or increased head circumference. "Cyclosporine-A-induced gingival overgrowth may be alleviated by inducing cell cycle arrest through the downregulation of CDC25A, CDK4/6, CYCLIN D, and pRB, along with the enhancement of SMAD3, SMAD4, and RB in gingival fibroblasts." (PMID 39727652, 2024).
Pca (1 paper, 2020). "The protein expression levels of CDK2, CDK4, CDK6, and phospho-Rb (Ser807/811) declined in quiescent Pca cells, and almost all of them began to recover at 12 and 16 h after quiescent LNCaP and PC-3 cell re-entry into the cell cycle, respectively." (PMID 33392189, 2020).
phyllodes tumor (1 paper, 2025). A benign, borderline, or malignant fibroepithelial neoplasm arising from the breast and rarely the prostate gland.
posterior fossa ependymoma (1 paper, 2020). A high grade ependymoma that is located within the posterior fossa. "We found that most cell-cycle-related genes were overexpressed in supratentorial and posterior fossa ependymomas, particularly cyclin D1 and CDK4, which can serve as actionable therapeutic targets." (PMID 33271970, 2020).
Pruritus (1 paper, 2023). Pruritus is an itch or a sensation that makes a person want to scratch. "The main significance was found for the multinomial logistic regression model for severity of the first toxicity as outcome and age, CDK4/6i, and pruritus as predictors." (PMID 37509319, 2023). "The multinomial logistic regression analysis reported a non-significant figure for age, type of CDK4/6i therapy, and pruritus in predicting the type of first onset cAE (p = 0.052; pseudo R2 = 0.12)." (PMID 37509319, 2023). "Pruritus occurred regardless of CDK4/6i type, and it seemed to be a class-related cAE; however, the specific underlying pathogenetic mechanisms remain unclear." (PMID 37509319, 2023).
retinal dystrophies (1 paper, 2020). "We previously identified that CDK4 is reactivated in various rodent models of inherited retinal dystrophies as well as during light damage and plays a role in the execution phase of photoreceptor death." (PMID 33324144, 2020).
round cell liposarcoma (1 paper, 2018). A poorly differentiated liposarcoma, characterized by the presence of solid sheets of primitive round mesenchymal cells and the absence of myxoid stroma. "An upregulation of CDK4 is described in 85% of myxoid and round cell liposarcoma." (PMID 29451912, 2018).
schizophrenia (1 paper, 2023). A major psychotic disorder characterized by abnormalities in the perception or expression of reality. "CDK4 expression is decreased in the acute state of schizophrenia." (PMID 36691005, 2023).
skin reaction (1 paper, 2023). "We tried to change the CDK4/6 inhibitor for one patient, but the skin reaction persisted." (PMID 36969030, 2023).
skin squamous cell carcinoma (1 paper, 2022). A carcinoma arising from the squamous cells of the epidermis. "In skin squamous cell carcinoma, miR-365a-3p plays an oncogenic role by downregulating nuclear factor IB to promote CDK6 and CDK4 expression, leading to Rb phosphorylation and tumor progression." (PMID 35682793, 2022).
skin toxicity (1 paper, 2025). "In cases of significant skin toxicity that does not respond to standard management strategies, switching to a different CDK4/6 inhibitor or adjusting the treatment regimen may offer a solution." (PMID 40422590, 2025).
spindle cell lipoma (1 paper, 2025). A benign circumscribed tumor composed of spindled cells, adipocytes, and collagen bundles. "For instance, the distinction between atypical lipomatous tumors and spindle cell lipoma often requires the confirmation of MDM2 and CDK4 amplification." (PMID 40870476, 2025).
Stroke (1 paper, 2018). Sudden impairment of blood flow to a part of the brain due to occlusion or rupture of an artery to the brain. "Indeed, the expression of cyclin D, Cdk4 and their specific targets E2F and pRB is increased following stroke or ischemic insult." (PMID 29581894, 2018).
T cell lymphomas (1 paper, 2022). "Interestingly, cyclin D3 and CDK4 are overexpressed in NOTCH-dependent T cell lymphomas, indicating that cell-cycle inhibitors and GSI should be used together to treat T cell lymphomas." (PMID 35681778, 2022).
tetanus (1 paper, 2007). A serious infectious disorder that follows wound contamination by the Gram-positive bacterium Clostridium tetani. "By the treatment of CDK4 inhibitor, the induction or the maintenance of Long-term potentiation (LTP) in response to a strong tetanus and NMDA receptor-dependent long-term depression (LTD) were normal in hippocampus." (PMID 17535444, 2007).
β-cell deficiency (1 paper, 2022). "This research indicates that GQD and metformin significantly increased the α-cell proliferation of β-cell deficiency induced diabetic rats by restoring Cdk4 and Irs1 gene expression." (PMID 35858880, 2022).
tumor (2,015 papers, 1995 to 2026). "L6565 exhibited homozygous CDKN2A loss with retained Rb expression, rendering tumour cells sensitive to CDK4/CDK6 inhibition via palbociclib." (PMID 41924733, 2026). "Dysregulation of this pathway – via cyclin D overexpression, CDK4/6 amplification or mutation, or the loss of CDK4/6 inhibitors or RB – can result in unchecked tumor cell proliferation." (PMID 40304827, 2025). "PD-L1 blockade alone delayed tumor growth but caused little tumor regression compared to combination CDK4/6-MEK and PD-L1 inhibition." (PMID 39857943, 2025). "These alterations lead to the loss of p16INK4a function, relieving its inhibition on CDK4/6 and promoting progression into the S phase, thereby facilitating tumor cell proliferation." (PMID 40182139, 2025). "Trials such as NCT02523014 now stratify patients based on SMO, AKT1, and CDK4/6 mutations, to individualize therapy to the tumor’s oncogenic circuitry." (PMID 40867323, 2025). "A newly published study provides important insight, showing that loss of the NF1/neurofibromin tumor suppressor confers greater sensitivity to CDK4/6 inhibition, as these tumors rely heavily on CDK4/6 activity for survival under endocrine therapy." (PMID 41226361, 2025). "A better understanding of these mechanisms is crucial for developing innovative strategies aimed at optimizing the use of CDK4/6 inhibitors, even in tumours with Rb deficiency or mutation, which are usually resistant to these agents." (PMID 41388212, 2025). "For example, in RB-deficient tumor models, the cell cycle is uncoupled from CDK4/6 kinases and D-type cyclins, rendering these proteins dispensable for cell cycle progression." (PMID 39924553, 2025). "Inhibition of MIF or loss of Mif in tumor cells reverses the immunostimulatory effects of CDK4/6i on macrophages and subsequent CD8+ T cell antitumor immunity." (PMID 41082324, 2025). "CDK4 was substantially linked with the T stage (p = 0.02), tumor status (p = 0.024), histologic grade (p = 0.032), and pathologic stage (p = 0.055), according to a logit regression analysis." (PMID 38231074, 2025). "Although its predictive value for atezolizumab efficacy is uncertain, CDK4 activation has been linked to an immunosuppressive tumor microenvironment, suggesting potential resistance to PD-L1 blockade." (PMID 41303594, 2025). "The secondary end point was OS in the clinical practice setting, defined as the time interval between tumor progression during ET plus CDK4/6i treatment and patient death from any cause." (PMID 39982725, 2025). "The suppressive anti-tumor immunity caused by CDK4/6is is primarily related to antigen presentation and the mediation of cellular senescence." (PMID 41463246, 2025). "Among these, the proteins encoded by MDM2 and CDK4 play a role in cell cycle regulation and are considered driving genes for this tumor type." (PMID 40674962, 2025). "Giredestrant (GDC-9545) is a SERD, active either as monotherapy or in association with a CDK4/6i in ESR1 mutant or wild-type tumor models." (PMID 40244377, 2025). "At the same time, binimetinib has been shown to be effective when combined with a CDK4 inhibitor (ribociclib), especially when CDK4 or cyclin D1 mutations were present in the tumor (overall response rate 32%)." (PMID 40361349, 2025). "Exploratory analysis from the MAINTAIN trial suggested that the presence of ESR1 mutation in circulating tumor DNA is detrimental to ‘maintaining’ CDK4/6i treatment." (PMID 40427107, 2025). "Given that TNBC-derived tumour cells often carry genetic mutations in the retinoblastoma (RB) protein, these cells are resistant to CDK4 inhibition." (PMID 40478388, 2025).